PRPF18 (pre-mRNA processing factor 18)
Description:
Participates in the second step of pre-mRNA splicing.
Synonyms: hPRP18; PRP18
Tractability: Small molecule: it has a binding pocket of medium quality. PROTAC: ubiquitination databases record sites on it; its protein half-life has been measured.
Gene: Protein-coding gene on chromosome 10 (13,586,939 to 13,668,445, forward strand). Ensembl gene ENSG00000165630.
Subcellular location: Nucleus speckle
Subcellular location (Human Protein Atlas): Nuclear speckles; Cytosol
Pathways (Reactome):
Metabolism of RNA: mRNA Splicing - Major Pathway
Gene Ontology:
Molecular function: protein binding
Biological process: generation of catalytic spliceosome for second transesterification step; mRNA processing; RNA splicing
Cellular component: nucleoplasm; nucleus; spliceosomal complex; U2-type post-spliceosomal complex; U4/U6 x U5 tri-snRNP complex; U5 snRNP; nuclear speck
Genetic constraint (gnomAD): Loss-of-function variants: 29 observed, 33.78 expected, observed/expected ratio (o/e) 0.86, 90% interval 0.64 to 1.17. The upper end of that interval is the gene's LOEUF score, 1.17, which puts it in group 5 of 6, group 1 being the genes least tolerant of losing a copy. Missense variants: 190 observed, 329.98 expected, observed/expected ratio (o/e) 0.58, 90% interval 0.51 to 0.65. Synonymous variants: 121 observed, 119.78 expected, observed/expected ratio (o/e) 1.01, 90% interval 0.87 to 1.17.
Homologues: Orthologues: chimpanzee PRPF18 (100% identical), guinea pig PRPF18 (100% identical), rabbit PRPF18 (99% identical), dog PRPF18 (99% identical), pig PRPF18 (99% identical), mouse Prpf18 (99% identical), rat Prpf18 (99% identical), macaque PRPF18 (94% identical), tropical clawed frog prpf18 (88% identical), zebrafish prpf18 (85% identical), Drosophila melanogaster Prp18 (50% identical), Caenorhabditis elegans prp-18 (38% identical).
Diseases named in the same sentence as PRPF18 in open-access papers:
PRPF18 is named in the same sentence as 7 diseases in open-access papers, as found by Europe PMC text mining. Sharing a sentence is not in itself a finding about the gene and the disease.
PRPF18 shares sentences with these, for which no sentence is quoted: amyotrophic lateral sclerosis (1 paper); entropion (1); infection (1); psoriasis (1); retinitis pigmentosa (1); spinal muscular atrophy (1); type 2 diabetes (1).